SEMA3A (semaphorin 3A)
Diseases named in the same sentence as SEMA3A in open-access papers (continued):
Sharing a sentence is not in itself a finding about the gene and the disease.
melanoma (9 papers, 2012 to 2022). A malignant, usually aggressive tumor composed of atypical, neoplastic melanocytes. "A number of studies showed that low levels of Sema3A were associated with non-small cell lung carcinoma and melanoma." (PMID 33546237, 2021). "Multiple in vitro approaches and in vivo mice models identified Sema3A as a tumor suppressor for melanoma." (PMID 33858502, 2021). "In particular, overexpression of Sema3A in melanoma models was able to suppress cell migration, invasion and proliferation, as well as to inhibit in vivo tumor growth, angiogenesis and metastasization." (PMID 33858502, 2021). "An enhanced response to dacarbazine and curcumin was also observed in melanoma cells expressing high levels of Sema3A." (PMID 33858502, 2021). "In fact, SEMA3E and its receptor PLXND1 was reported to promote tumor invasiveness and metastatic spreading of melanoma in mice, and SEMA3A was found to suppress tumor growth and metastasis in melanoma." (PMID 32640719, 2020). "Mouse melanoma (B16F10) cells overexpressing Sema3A show a significant inhibition of cell motility, invasiveness and proliferation, as well as suppression of tumor growth in vivo, and angiogenesis and metastasis in mice models." (PMID 25961819, 2015). "Xenografts derived from SEMA3A-transfected melanoma cells also exhibit poor vascularization and a non-metastatic phenotype." (PMID 26755661, 2016).
schizophrenia (9 papers, 2009 to 2025). A major psychotic disorder characterized by abnormalities in the perception or expression of reality. "An elevated level of Sema3A in the cerebellum of patients with schizophrenia is associated with the downregulation of genes related to the formation and maintenance of synapses, thereby reducing synaptic plasticity." (PMID 36776771, 2022). "The SEMA3A protein has been shown to be upregulated in schizophrenia patients and is suggested to contribute to the developmentally induced impairment of synaptic connectivity in the disorder." (PMID 36882310, 2023). "The overexpression of Sema3a can lead to nerve diseases, such as schizophrenia, but defects in Sema3a result in abnormal neuronal innervation." (PMID 29403069, 2018). "Members of the semaphorin family, and semaphorin 3a in particular, have also been shown to be altered in schizophrenia, potentially in conjunction with Reelin." (PMID 26839720, 2016). "In particular, increased semaphorin 3A and decreased Reelin expression were detected in the cerebellum of subjects with schizophrenia, while altered expression of multiple members of the semaphorin family was observed in the prefrontal cortex." (PMID 26839720, 2016).
acute kidney injury (8 papers, 2013 to 2024). Sudden and sustained deterioration of the kidney function characterized by decreased glomerular filtration rate, increased serum creatinine or oliguria. "The magnitude of rise supports the notion that semaphorin 3A represents a useful early diagnostic biomarker of acute kidney injury." (PMID 23469280, 2013). "Here we describe the identification and validation of a new early diagnostic biomarker, semaphorin 3A, for acute kidney injury." (PMID 23469280, 2013). "Accumulated evidence has suggested importance roles of SEMA3A signaling in kidney development and several kidney diseases, including proteinuric diseases, acute kidney injury (AKI) and CKD." (PMID 37835781, 2023). "In vivo and in vitro experiments have shown that EGCG inhibited the expression of Sema3A and attenuated inflammation and apoptosis in rodents with lipopolysaccharide-induced acute kidney injury." (PMID 36776771, 2022). "Sema3A enhances LPS-induced acute kidney injury by increasing Rac1 (a key factor for activation of NF-κB) and p65 and augments LPS-induced macrophage activation and cytokine production in a plexin-A4–dependent manner." (PMID 34039431, 2021). "For example, urinary SEMA3A has been shown to be an early, predictive biomarker of acute kidney injury (AKI) as well as later-onset AKI and progression of AKI." (PMID 32521824, 2020). "SEMA kinetics were related to sepsis complications; SEMA3A, SEMA3C, SEMA3F, and SEMA4D with respiratory failure; SEMA3C and SEMA7A with acute kidney injury; and SEMA3C and SEMA3F were related to septic shock." (PMID 39770766, 2024). "Here, we determined whether semaphorin3A is induced after acute kidney injury (AKI) and whether urinary semaphorin 3A can predict AKI in humans undergoing cardiopulmonary bypass (CPB)." (PMID 23469280, 2013). "Furthermore, the kinetics of SEMA were related to sepsis complications; SEMA3A, SEMA3C, SEMA3F, and SEMA4D were related to respiratory failure; SEMA3C and SEMA7A were related to acute kidney injury, while SEMA3C and SEMA3F were related to septic shock." (PMID 39770766, 2024). "Therefore, the objective of this study was to determine the expression pattern in animal models of AKI, its functional role in AKI, and whether urinary semaphorin 3A levels predict the development of AKI in animal and human acute kidney injury." (PMID 23469280, 2013).
gastric cancer (8 papers, 2017 to 2025). A primary or metastatic malignant neoplasm involving the stomach. "The authors observed that overexpression of Sema3A significantly attenuated the proliferation, migration, and invasiveness of gastric cancer cells, and this effect was associated with the inhibition of the PI3K/Akt pathway and reduced NRP-1 expression." (PMID 40430075, 2025). "Increased SEMA3A expression was associated with better prognosis in patients with cancer, including epithelial ovarian carcinoma, gastric cancer, tongue cancer, and HNC." (PMID 32842711, 2020). "Decreased expression of SEMA3A in gastric carcinomas was associated with poor differentiation and with invasion and metastasis." (PMID 28611294, 2017). "In a recent study with gastric cancer cells, SEMA3A overexpression was shown to arrest the proliferation, migration, and metastatic properties of cancer cells." (PMID 40318008, 2025). "A previous study documented downregulated expression of SEMA3A in gastric cancer (GC) cells, and SEMA3A overexpression was found to impede GC cell proliferation, migration, invasion, and EMT." (PMID 39177014, 2024). "Overexpression of SEMA3A in the gastric cancer cell line SGC-7901 inhibited cell proliferation and migration in vitro." (PMID 29649113, 2018). "SEMA3A is a putative tumour suppressor and is often downregulated in different types of cancer, including gastric cancer, ovarian cancer and tongue cancer." (PMID 29649113, 2018). "According to recent reports, Sema3A may play an antitumor role in gastric cancer by acting as an inhibitor of NRP-1 activity." (PMID 40430075, 2025). "Moreover, overexpression of SEMA3A inhibits gastric cancer cell proliferation and migration in vitro." (PMID 32842711, 2020). "However, SEMA3A expression decreases significantly as gastric cancer progresses and metastasizes, suggesting that SEMA3A may serve as a candidate tumor suppressor." (PMID 29784063, 2018).
Obesity (8 papers, 2020 to 2025). Accumulation of substantial excess body fat. "Genetic variations in SEMA3A have been reported to be associated with severe early onset obesity owing to disrupted SEMA3A signaling in pro-opiomelanocortin (POMC)-expressing anorexigenic neurons." (PMID 38541683, 2024). "Several Sema3 members have been reported to regulate obesity by regulating adipogenesis (with an inhibitory role for Sema3A and a stimulatory role for Sema3G) and hypothalamic melanocortin circuits development (mutations of Sema3 and their receptors resulting in early onset of obesity)." (PMID 32781674, 2020). "During obesity, the upregulation of SEMA3A leads to defenestration, which ultimately results in hepatic steatosis." (PMID 40562785, 2025). "Here we demonstrate that Sema3a is elevated in liver sinusoidal endothelial cells of animal models for obesity, type 2 diabetes and MASLD." (PMID 39196233, 2024). "The class-3 semaphorin subfamily (Sema3A–3G) is involved in obesity and metabolic disorders, and utilizes neuropilins and plexins as their main binding receptors." (PMID 37576981, 2023). "Among the five semaphorin classes in vertebrates, the Class-3 semaphorin subfamily (Sema3A–3G) is the most studied semaphorins in metabolic disorders from obesity to diabetic complications." (PMID 32781674, 2020). "Notably, SEMA3A has also been implicated in conditions that are frequently associated with DOR, such as obesity." (PMID 38541683, 2024). "We conclude that in obesity, Sema3a is haplo-insufficient for promoting early stage MASLD." (PMID 39196233, 2024). "In support of this evidence, a lack of Nrp1 in GnRH neurons in mice leads to obesity, thus revealing the previously unrecognized role of SEMA3A and the GnRH system in maintaining energy homeostasis." (PMID 38541683, 2024).
Alzheimer disease (7 papers, 2017 to 2025). A progressive, neurodegenerative disease characterized by loss of function and death of nerve cells in several areas of the brain leading to loss of cognitive function such as memory and language. "Hippocampal accumulation of SEMA3A in early stages of Alzheimer ́s disease suggested a link to neurodegenerative processes." (PMID 28158247, 2017).
depression (7 papers, 2020 to 2025). "Research indicates that Sema3A, a molecule elevated in certain mental illnesses, is associated with severe depression." (PMID 41409594, 2025). "In agreement with our findings, a previous GWAS found an association with a locus at a different class of semaphorin, SEMA3A, to be associated with decreased risk of alcohol dependence and major depression in African Americans." (PMID 37550624, 2023). "An elevated level of Sema3A in the CNS was linked to various psychiatric disorders and Sema3A risk variants were related to major depression." (PMID 36776771, 2022). "The specific contribution of Sema3A mutations to the possible causes of alcohol dependence and depression remains to be elucidated." (PMID 34045951, 2021). "Importantly, EGCG alleviated gestational stress-induced postpartum anxiety and depression symptoms, which was associated with the downregulation of Sema3A and increase of phosphorylated GSK3β in the hippocampus." (PMID 36776771, 2022). "As a downstream target of Sema3A, GSK3β is thought to be associated with major depression." (PMID 36776771, 2022). "As a downstream target of Sema3A, glycogen synthase kinase 3β (GSK3β) is thought to play a role in depression pathology." (PMID 41409594, 2025). "In the present study, we found that Sema3A expression in the hippocampus was increased in a mouse model of PPD, which was associated with anxiety and depression-like symptoms." (PMID 36776771, 2022). "Gestational stress induced anxiety and depression-like behaviors during the postpartum period, increasing Sema3A expression while decreasing that of phosphorylated GSK3β as well as c-Fos in the hippocampus." (PMID 36776771, 2022). "Additionally, variants of the Sema3A gene are found to be linked to comorbid alcohol dependence and major depression, suggesting a role for Sema3A in the etiology of depression." (PMID 36776771, 2022). "In the present work, treatment with EGCG reduced anxiety and depression-like behaviors in PPD mice and reversed the increase of hippocampal Sema3A expression induced by gestational stress, indicating that it had protective effects against anxiety and depression in the postpartum period." (PMID 36776771, 2022). "An elevated level of Sema3A in the central nervous system (CNS) including the hippocampus and cerebellum has been observed in various neurologic and psychiatric diseases, but its role in depression is not fully understood." (PMID 36776771, 2022). "In this framework, Sema3A or other plasticity inhibitors of the Semaphorin family may be interesting targets to treat depression." (PMID 34045951, 2021). "Thus, EGCG may alleviate anxiety and depression-like behaviors in mice by downregulating Sema3A and increasing GSK3β phosphorylation in the hippocampus, and has potential application in the treatment of PPD." (PMID 36776771, 2022). "Although Sema3A, GSK3β, and CRMP2 have been linked to depression, their role in PPD has not been reported." (PMID 36776771, 2022).
diabetic nephropathy (7 papers, 2015 to 2024). "Pharmacological inhibition with a novel Sema3A inhibitory peptide has been shown to protect against diabetic nephropathy." (PMID 32781674, 2020). "A very recent study further elucidated the role of Sema3A in DN as the authors demonstrated that Sema3A promotes diabetic nephropathy." (PMID 26239560, 2015). "In diabetic nephropathy, sema3a was regarded as a target of miR-15b-5p to induce podocyte injury." (PMID 31481931, 2019).
diabetic retinopathy (7 papers, 2015 to 2025). "Neutralization antibodies of Sema3A alleviates vascular hyperpermeability in early diabetic retinopathy and neurodegeneration in OIR." (PMID 32781674, 2020). "Recently, a study demonstrated that sema3a plays an important role in mediating the breakdown of barrier function in diabetic retinopathy." (PMID 26554379, 2015). "Notably, the Sema3A-Nrp1 signaling pathway has been identified for its significant involvement in the pathogenesis of diabetic retinopathy." (PMID 37830626, 2023). "Serum Sema3A levels have also correlated with the phenotypes of diabetic retinopathy." (PMID 32781674, 2020). "Background literature was searched in PubMed using search terms such as ‘diabetic retinopathy’, ‘diabetic macular ischemia’, ‘diabetic macular edema’, ‘semaphorin 3a’, ‘neuropilin 1’, ‘retinal non-perfusion’, ‘vascular perfusion’, ‘anti-VEGF’, ‘corticosteroid’ and ‘laser photocoagulation’." (PMID 40634736, 2025).
hypogonadotropic hypogonadism (7 papers, 2017 to 2024). Abnormal ovarian or testicular function due to insufficient hormonal stimulation from the hypothalamic-pituitary axis. "A unique homozygous and clinically relevant variant was identified in the SEMA3A gene, which may contribute to neural development and his phenotypic spectrum including short stature and isolated hypogonadotropic hypogonadism (IHH)." (PMID 32612575, 2020). "SEMA3A variants were reported in patients of hypogonadotropic hypogonadism (OMIM#614897)." (PMID 28295047, 2017). "We also found novel FGFR1 and SEMA3A variants that suggest an oligogenic mechanism in PSIS and EPP, as seen in patients with hypogonadotropic hypogonadism." (PMID 39156017, 2024). "In addition, SEMA3A and SEMA3E (Semaphorin 3E), are also reported to be associated with hypogonadotropic hypogonadism." (PMID 32390946, 2020).
multiple sclerosis (7 papers, 2017 to 2024). A progressive autoimmune disorder affecting the central nervous system resulting in demyelination. "Strikingly, an analysis of human multiple sclerosis sample tissues and the use of an experimental model of demyelination revealed a clear spatio‐temporal regulation of Sema3A expression, thereby strengthening the idea of a role of Semaphorins in myelination." (PMID 31566924, 2019). "In addition to this primary role, SEMA3A also has an important secondary role in inhibiting myelin regeneration in multiple sclerosis, at least in part by inhibiting oligodendrocyte precursor cell differentiation and recruitment to demyelinated lesions." (PMID 38438384, 2024). "Recent studies have also shown that Sema3A increase in ALS is not limited to the periphery, but it is also a central phenomenon affecting motor neurons in the motor cortex of sporadic ALS patients, astrocytes in cases of spinal cord injury and oligodendrocytes in multiple sclerosis." (PMID 30711519, 2019).
ovarian carcinoma (7 papers, 2018 to 2025). A malignant neoplasm originating from the surface ovarian epithelium. "SEMA3A is a tumor suppressor gene, and its decreased expression was observed in gastric and ovarian cancer and correlated with disease progression and poor prognosis." (PMID 41465532, 2025). "Previously, we described downregulation of SEMA3A expression in three from four ovarian cancer PAC-resistant cell lines, and in the W1-PAC-resistant cell line, its expression was regulated by miR-145." (PMID 35008952, 2022). "The downregulation of SEMA3A as a tumor suppressor gene was described in many cancers, including ovarian cancer." (PMID 35008952, 2022). "Other findings have suggested that decreased Sema3A expression may be associated with the development of epithelial ovarian carcinoma, and therefore, Sema3A may be a valuable prognostic marker and a potential molecular therapy target for ovarian cancer patients." (PMID 30155491, 2018). "In gastric and ovarian cancer, downregulation of SEMA3A expression is correlated with disease progression and poor prognosis." (PMID 29649113, 2018). "Significant downregulation of SEMA3A expression was also observed in epithelial ovarian cancer in comparison to normal epithelium." (PMID 29649113, 2018). "FAM198B may act to favor tumor progression by interacting with numerous genes, such as the p-ERK/MMP-1 signaling pathway in lung adenocarcinoma, and S100A3, PCDH9, and SEMA3A genes in ovarian cancer." (PMID 35587159, 2022). "It was reported instead that Sema3A mRNA and protein expression is lower in ovarian carcinoma compared to normal tissue, and tumors with lowest levels are significantly associated with higher FIGO stage, histological grade, and the presence of lymphatic and distant metastasis." (PMID 33537086, 2021). "Recently, we described SEMA3A downregulation in three PAC-resistant ovarian cancer cell lines." (PMID 32283808, 2020). "Sema3A could therefore represent a valuable prognostic marker for ovarian cancers; moreover, its activity could be potentially exploited for therapeutic approaches, currently validated in other preclinical tumor models in mice 54,55, as discussed later in this review." (PMID 33537086, 2021).
Arthritis (6 papers, 2017 to 2025). Inflammation of a joint. "Our findings uncovered Sema3A as a promising diagnostic biomarker and novel prevention and treatment strategies in arthritis treatment." (PMID 29029510, 2017). "They showed that Sema3A administration in mice reduced arthritis incidence and disease severity, accompanied by a decrease in IFN-γ and IL-17 serum levels and an increase in IL-10 levels." (PMID 41303643, 2025). "Together, these finding show that Sema3A modulates cytokine production and promotes regulatory T-cell functions, thereby attenuating inflammatory responses in arthritis." (PMID 41303643, 2025). "MiR-145-5p targets osteoprotegerin, aggravating bone erosion in collagen-induced arthritis, and also regulates semaphorin 3A (SEMA3A) to modulate the phenotype of RA FLS." (PMID 32850892, 2020). "A low expression of Sema3A in the CD4+ T cells and synovial tissues of RA patients and an alleviation of collagen-induced arthritis by Sema3A overexpression have been previously reported." (PMID 30538782, 2018). "One of these was assessing the beneficial therapeutic effect of sema3A in a mouse model of collagen-induced arthritis." (PMID 29670620, 2018). "Our in vivo data demonstrated that Sema3A administration attenuated joint tissue damage and the severity of experimental arthritis." (PMID 29029510, 2017). "We used this STA model to test the role of Sema3A in RA, our in vivo data demonstrated that Sema3A administration protected the progression of arthritis, and significantly decreased the osteoclastogenesis and protected the joint tissue damage." (PMID 29029510, 2017). "In vivo data demonstrated that Sema3A administration attenuated joint tissue damage and the severity of experimental arthritis." (PMID 29029510, 2017). "Finally, we used the serum-transfer induced arthritis (STA) model to investigate the therapeutic potential of Sema3A in RA." (PMID 29029510, 2017). "Moreover, Sema3A overexpression attenuated collagen-induced arthritis." (PMID 30538782, 2018).